PEX12 (peroxisomal biogenesis factor 12)
Description:
Component of a retrotranslocation channel required for peroxisome organization by mediating export of the PEX5 receptor from peroxisomes to the cytosol, thereby promoting PEX5 recycling. The retrotranslocation channel is composed of PEX2, PEX10 and PEX12; each subunit contributing transmembrane segments that coassemble into an open channel that specifically allows the passage of PEX5 through the peroxisomal membrane (By similarity). PEX12 also regulates PEX5 recycling by activating the E3 ubiquitin-protein ligase activity of PEX10. When PEX5 recycling is compromised, PEX12 stimulates PEX10-mediated polyubiquitination of PEX5, leading to its subsequent degradation (By similarity).
Synonyms: PAF-3; PBD3A
Tractability: Antibody: UniProt predicts a signal peptide or a membrane-spanning region. PROTAC: its protein half-life has been measured.
Gene: Protein-coding gene on chromosome 17 (35,574,795 to 35,578,863, reverse strand). Ensembl gene ENSG00000108733.
Subcellular location: Peroxisome membrane
Pathways (Reactome):
Protein localization: Class I peroxisomal membrane protein import; Peroxisomal protein import
Metabolism of proteins: E3 ubiquitin ligases ubiquitinate target proteins
Gene Ontology:
Molecular function: protein binding; ubiquitin ligase activator activity; ubiquitin protein ligase activity; zinc ion binding; protein transmembrane transporter activity
Biological process: cellular response to reactive oxygen species; peroxisome organization; protein import into peroxisome matrix; protein import into peroxisome matrix, receptor recycling; protein polyubiquitination; proteasome-mediated ubiquitin-dependent protein catabolic process; protein import into peroxisome matrix, substrate release; protein quality control for misfolded or incompletely synthesized proteins; protein targeting to peroxisome; protein ubiquitination
Cellular component: peroxisomal membrane; peroxisome; ubiquitin ligase complex; cytosol; peroxisomal importomer complex
Genetic constraint (gnomAD): Loss-of-function variants: 31 observed, 34.36 expected, observed/expected ratio (o/e) 0.9, 90% interval 0.68 to 1.22. The upper end of that interval is the gene's LOEUF score, 1.22, which puts it in group 5 of 6, group 1 being the genes least tolerant of losing a copy. Missense variants: 359 observed, 442.31 expected, observed/expected ratio (o/e) 0.81, 90% interval 0.74 to 0.89. Synonymous variants: 148 observed, 166.25 expected, observed/expected ratio (o/e) 0.89, 90% interval 0.78 to 1.02.
Gene-disease validity (ClinGen):
ClinGen rates the evidence that PEX12 causes each of these diseases.
peroxisome biogenesis disorder (autosomal recessive): Definitive.
Homologues: Orthologues: chimpanzee PEX12 (99% identical), macaque PEX12 (98% identical), pig PEX12 (93% identical), rabbit PEX12 (93% identical), guinea pig PEX12 (92% identical), dog PEX12 (92% identical), mouse Pex12 (89% identical), rat Pex12 (89% identical), tropical clawed frog pex12 (65% identical), zebrafish pex12 (59% identical), Caenorhabditis elegans prx-12 (34% identical), Drosophila melanogaster Pex12 (24% identical).
Diseases named in the same sentence as PEX12 in open-access papers:
PEX12 is named in the same sentence as 14 diseases in open-access papers, as found by Europe PMC text mining. Sharing a sentence is not in itself a finding about the gene and the disease. The quoted sentences say what the papers report.
peroxisome biogenesis disorder (4 papers, 2008 to 2026). "Of note, mutations in human PEX12 result in Zellweger syndrome, one of a group of several related diseases called peroxisome biogenesis disorders, which are part of a larger group of diseases known as the leukodystrophies." (PMID 18941528, 2008). "Laboratory studies were unremarkable, but trio whole-exome sequencing identified a homozygous PEX12 deletion (c.1047_1049del), confirming a diagnosis within the Zellweger spectrum of peroxisome biogenesis disorders." (PMID 42151956, 2026). "For peroxisomal biogenesis disorders, premature termination codon mutations in PEX2 and PEX12 have previously been analyzed showing improved metabolic activity after G418 treatment." (PMID 34356630, 2021).
Zellweger syndrome (4 papers, 2008 to 2025). "Approximately 80% of PBD patients are classifiedin the Zellweger syndrome spectrum, which is generally caused by mutations in the PEX1, PEX6, PEX10, PEX12, or PEX26 genes." (PMID 33912394, 2021). "Zellweger spectrum disorders (ZSDs), including archetypal Zellweger syndrome, neonatal adrenoleukodystrophy (NALD) and infantile Refsum disease (IRD), are PBDs caused by mutations in peroxin genes (PEX1, PEX2, PEX3, PEX5, PEX6, PEX10, PEX11β, PEX12, PEX13, PEX14, PEX16, PEX19 or PEX26)." (PMID 40949164, 2025).
parotid tumor (1 paper, 2021). "Only PEX11 and PEX12 were differentially upregulated in parotid tumor tissue compared healthy parotid tissue." (PMID 34360635, 2021).
tumor (3 papers, 2021 to 2025). "In contrast, analysis for mRNAs encoding for peroxisomal biogenesis proteins (Pex7, Pex10, Pex12), and proteins for peroxisomal proliferation (Pex11α, Pex11β) were significantly upregulated in PMA tumor compared to control tissue." (PMID 34360635, 2021).
neoplastic disorders (1 paper, 2025). "PEX2 and other peroxins—namely, PEX5, PEX10, and PEX12—play a pivotal role in ensuring the survival of malignant cells and, consequently, emerge as prospective therapeutic targets for combating neoplastic disorders." (PMID 40487257, 2025).
neurological disorders (1 paper, 2021). "Mutations in PEX12 have been recently correlated with progressive neurological disorders." (PMID 33803845, 2021).
PEX12 also shares sentences with these, for which no sentence is quoted: breast carcinoma (1 paper); Breast Invasive Carcinoma (1); glioma (1); infantile Refsum disease (1); leukodystrophies (1); liver dysfunction (1); optic atrophy (1); Seckel syndrome (1).